FOXA2 (forkhead box A2)
Diseases named in the same sentence as FOXA2 in open-access papers (continued):
Sharing a sentence is not in itself a finding about the gene and the disease.
tumor (continued). "LncRNA neighboring enhancer of FOXA2 (NEF) was first discovered as a tumor suppressor in hepatocellular carcinoma by reversing the EMT process and inhibiting tumor metastasis." (PMID 35573683, 2022). "It has been shown to regulate tumor cell growth and metastasis via a variety of downstream target genes, including Selenbp1, EGFR, Foxa2, CDX2, and DDB1." (PMID 36614938, 2022). "FOXA2 can inhibit the transcription of metalloproteinase-9 (MMP-9) and can attenuate the invasion and metastasis of tumor cells." (PMID 31689237, 2019). "Forkhead box A2 (FOXA2)-induced lncRNA-NEF is frequently down-regulated in HCC, and suppresses epithelial-mesenchymal transition (EMT) and tumor metastasis by antagonizing Wnt/β-catenin pathway." (PMID 30782188, 2019). "For example, a cis-positive feedback loop exists for the tumor suppressor molecules lncRNA-NEF and forkhead box A2 (FOXA2)." (PMID 31097003, 2019). "When the lncRNA and messenger RNA (mRNA) data from LUAD were merged and compared, FOXA2 showed the strongest correlation with LINC00261 expression in both normal and tumor samples independently in the LUAD and the LUSC datasets." (PMID 30597925, 2018). "By IHC, we confirmed upregulation of AFP, FOXA2 and EOMES in a subset of cells morphologically appearing differentiated within TCam-2-ΔSOX2 tumor tissues." (PMID 27283990, 2016). "While the observed decrease in metastatic activity caused by FOXA2 KD was consistent with a role of FOXA2 in metastasis, an alternative explanation might be that FOXA2 KD has a general suppressive effect on SCLC cell proliferation and tumor growth." (PMID 40419484, 2025). "While some SCLC metastases demonstrated strong and consistent FOXA2 expression by IHC, others demonstrate both FOXA2-positive and -negative cancer cells in the same tumor section." (PMID 40419484, 2025). "NKX2-1/FOXA2 further recruits p300/CBP to activate NE enhancers, and pharmacological inhibition of p300/CBP effectively blunts NE gene expression and abolishes NEPC tumor growth." (PMID 40691407, 2025). "Additionally, the expression levels of FOXP3, FOXO3, FOXO1, FOXA2, and FOXM1 were found to be elevated in GBM tissues from the TCGA database compared to non-tumor brain tissues, while the level of FOXQ1 was reduced." (PMID 38561331, 2024). "The oestrogen-ERα axis can also play a role in tumour promotion in the absence of Foxa1 and Foxa2 in the receptor complex." (PMID 37752418, 2023). "Importantly, FOXA2 has been described as an epithelial marker and inhibitor of EMT in several tumor types." (PMID 32414223, 2020). "Moreover, miR-1291 directly affects a variety of metabolic pathways, such as fork head box protein A2 (FOXA2) and glucose transporter 1 (GLUT1), to affect the growth and invasion of tumor cells 4,5." (PMID 32641987, 2020). "These analyses also showed an enrichment for hypomethylated binding sites of transcription factors (e.g., ESR1, ESR2, FOXA2) and histone proteins (e.g., H3K4m1, H3K4m2, H3K4m3, H3K27m3, H3K9m3) in GBM2 compared to GBM1, suggesting a role for these factors in tumor progression." (PMID 32779022, 2020). "At 20 weeks after TAA administration, FoxA2-/- mice displayed significant manifestations of neoplasia, while WT mice did not." (PMID 31689237, 2019). "We found expression of pluripotency factors OCT3/4, LIN28 and NANOG in the TCam-2-ΔSOX2/FOXA2 tumor tissues, but not of PRDM14, which is strongly upregulated in TCam-2 cells, which were reprogrammed to an EC-like cell fate." (PMID 31130628, 2019). "Consistently, data from expression profiling by high-throughput sequencing suggested that FOXA2 mRNA was significantly lower in tumor samples compared with paired noncancerous tissue (GSE119336, Provided by Zhou G, Cao P and Li Y)." (PMID 31689237, 2019).
tumor (continued). "When Nkx2-1, Foxa1 and Foxa2 are deleted at tumor initiation, the resulting lung lesions lacked evidence of either pulmonary or gastric differentiation." (PMID 30475207, 2018). "In the non-tumor settings, LINC00261 is strongly expressed in endodermal tissues and drives the endoderm differentiation by upregulating the expression of the endoderm differentiation factor FOXA2." (PMID 30597925, 2018). "Respectively 3/20 G3 HRO tumours were specified by ARHGAP35 at 19q13.32 and by FOXA2 at 20p11.21." (PMID 28486536, 2017). "Moreover, FOXA1, FOXA2, and FOXA3 were also grouped together with the tumor/invasion suppressor genes EPHB2 and EPHB3, and with the intestine-specific differentiation genes CDX1 and CDX2 (cluster 2)." (PMID 29155818, 2017). "Hence, FOXA2 is likely to be regulating some of the many transcripts that are differentially expressed between MSS and MSI tumours." (PMID 19156145, 2009). "Consistently across these assays, FOXA2 KD did not suppress subcutaneous tumor growth." (PMID 40419484, 2025). "Limited FOXA2 locus chromatin accessibility was evident in the never-met tumor, and we considered the possibility that this might arise from intratumoral heterogeneity of cell states." (PMID 40419484, 2025). "Furthermore, FOXA2 stimulates the promoter of E-cadherin and inhibits EMT formation in tumor cells." (PMID 38605023, 2024). "Interestingly, according to the RNA-seq results of 15 pairs of ICC tumors and matched nontumor liver tissues, FOXA2 was significantly downregulated in the paired tumor samples (p=0.0028)." (PMID 31689237, 2019). "Interestingly, MDA231 triple negative-like cells expressed high levels of FoxA2 but not FoxA1, and the non-tumour HMECs did not express these factors." (PMID 27045898, 2016). "Transitional states with cytoplasmic localization of both Foxa2 and E-cadherin suggestive of neosynthesis in single MTC cells further support the idea that EMT is a highly dynamic and reversible process, possibly influenced by the immediate tumor cell microenvironment." (PMID 26395490, 2015). "Therefore functional knockdown of FOXA2 recovered HNF6 activity and inhibited growth of tumor-cells and may possibly represent a novel therapeutic target in primary and secondary liver malignancies." (PMID 20967225, 2010). "To obtain a more definitive result, we also performed ATAC-seq analysis on an ASCL1+ PDX tumor that was homogeneously negative for FOXA2, in comparison to 3 ASCL1+/FOXA2+ PDX tumors." (PMID 40419484, 2025). "To this end, we isolated cells derived from non-depleted (Dox−) FoxA1 or FoxA2 MCF7 and MDA231 tumours (control groups, GFP+/tRFP−), FoxA1- and FoxA2-depleted MCF7 and MDA231 tumours (GFP+/tRFP+), and the corresponding FoxA family-rescued tumours (GFP+/tRFP+), respectively." (PMID 27045898, 2016).
cancer (101 papers, 2009 to 2026). A tumor composed of atypical neoplastic, often pleomorphic cells that invade other tissues. "First, we documented that FOXA2 protein was downregulated in primary human ECs in a grade-dependent manner and was lost in most grade 3 cancers, suggesting that there is strong selection for FOXA2 loss during EC progression." (PMID 35703180, 2022). "FOXA1 and FOXA2 TFs contribute to the maintenance of epithelial cell identity and their deregulated expression is associated with cancer formation." (PMID 36509813, 2022). "Characterization of FOXA2 expression in human EC cell lines and primary tumors implicates loss of FOXA2 expression as a cancer driver." (PMID 35703180, 2022). "This cooperativity appeared to extend to cancers in general given that examination of all TCGA data sets revealed statistically significant co-occurrence of FOXA2 and PTEN mutations (log2 odds ratio 1.30, P < 0.001)." (PMID 35703180, 2022). "In uterine cancer, FOXA2 is frequently mutated and act as a pathogenic driver gene in the etiology of this cancer." (PMID 33344262, 2020). "The fact that FOXA2-DS-S has the same effect on the phenotypic characteristics of cancer cells as its associated gene is consistent with its positive effect on the expression of FOXA2 and the observation that it regulates a similar cohort of genes." (PMID 29540241, 2018). "FOXA1 and FOXA2 are also associated with a variety of cancers, and their behaviors are tumor type-specific, with a dependence on the particular transcriptome interactions." (PMID 30360388, 2018). "Colorectal liver metastases is a major cause of cancer morbidity and this study aimed for an improved understanding of an inhibitory cross talk of FOXA2 and HNF6 in secondary liver malignancies." (PMID 20967225, 2010). "In addition, further understanding of miRNA-mRNA and miRNA-epigenetic feedback loop would help in identifying potential novel therapeutic strategies and targets that are not limited to FOXA2 mutations but include cancer and regenerative medicine." (PMID 36749553, 2023). "Concordantly, differences in FOXA1 and FOXA2 mutational spectra in cancer are striking." (PMID 35703180, 2022). "In this study, we created a genetically engineered model of FOXA2-deficient EC and used it in combination with human and mouse cancer cell line systems to address diverse critical questions relating to the biological roles of FOXA2 in EC initiation and progression." (PMID 35703180, 2022). "Moreover, CDH1 and FOXA2 are linked to each other in carcinoma progression, evidenced by the loss of silencing FOXA2 leading to E-cadherin downregulation, EMT and metastasis." (PMID 34827193, 2021). "Whether the SUMOylation of FOXA2 or FOXL2 directly affects lipid metabolism as part of the mechanism underlying cancer development is yet to be determined." (PMID 32781719, 2020). "Thus, LINC00261 is a lncRNA associated with diverse forms of cancer, is highly conserved evolutionarily, and is co-regulated with its neighboring gene FOXA2 during EMT and tumorigenesis." (PMID 30597925, 2018). "The effects of FOXA2 on cell proliferation, migration, invasion, and cancer stem cell traits were evaluated using small interfering RNA (siRNA)-mediated silencing." (PMID 41799508, 2026). "Functionally, FOXA2 knockdown inhibited the proliferation, migration, invasion, and cancer stem cell properties of TamR cells while restoring tamoxifen sensitivity." (PMID 41799508, 2026). "We assessed differential gene expression between FOXA2+ (N = 19,617) and FOXA2– cancer cells (N = 16,643) within these SCLC tumors." (PMID 40419484, 2025). "Previous studies have shown that FOXA2 can promote cell growth and sustain the presence of cancer stem cells in TNBC." (PMID 40003882, 2025). "Consistent with the bulk RNA expression data above, we observed an increased expression of defined lung progenitor single cell signatures such as “fetal lung pulmonary neuroendocrine precursor” in FOXA2+ compared to FOXA2– cancer cells." (PMID 40419484, 2025).
cancer (continued). "For example, FOXP2, which is also a tumor suppressor, can interact with FOXA2 to inhibit the EMT of cancer cells." (PMID 40003882, 2025). "We also examined the expression of ABAT and FOXA2 across various cancer types using the TCGA database." (PMID 39972344, 2025). "A UMAP (Uniform Manifold Approximation and Projection) embedding of scRNA-seq data from 11 primary SCLC lung tumors confirmed that FOXA2 expression was primarily restricted to the cancer cell compartment in SCLC tumors." (PMID 40419484, 2025). "FOXA1 and FOXA2 play a synergistic role in organ development, but in some cases, FOXA1 and FOXA2 have opposite effects on glulipid metabolism and cancer development." (PMID 38605023, 2024). "This article focuses on the molecular mechanisms and clinical relevance of FOXA1 and FOXA2 in steroid hormone-induced malignancies and highlights potential strategies for targeting FOXA1 and FOXA2 for cancer therapy." (PMID 38605023, 2024). "The present article describes in detail the mechanisms and clinical applications of FOXA1 and FOXA2 in organ development and differentiation, metabolic reprogramming, metabolic diseases, and cancer development." (PMID 38605023, 2024). "FOXA2 suppression by TRIM36 was found to exert an anti-cancer function in colorectal cancer (CRC) by promoting NRF2/GPX4-mediated ferroptosis, emphasizing the potential of targeting the Nrf2/GPX4 pathway for therapeutic interventions in cancer." (PMID 39036600, 2024). "FOXA1- and FOXA2-mediated metabolism not only occurs under physiological conditions but is also widely found in pathological conditions, such as inflammation and cancer." (PMID 38605023, 2024). "This work discusses the roles of FOXA1 and FOXA2 in organ development, glycolipid metabolism, hormone signaling pathway transduction, and cancer drug resistance and their functions as pioneer factor." (PMID 38605023, 2024). "In triple-negative breast cancer, FOXA2 promotes cell proliferation, maintains cancer stem cells, facilitates the development of triple-negative basal-like tumors, and is associated with recurrence." (PMID 38605023, 2024). "Overall, our findings underscore the pivotal role of FOXA2 as a pan-plasticity driver that rewires AP-1 to induce the differential transcriptional reprogramming necessary for cancer cell lineage plasticity." (PMID 38851846, 2024). "Recently, STING was evidently defined to be enriched in the promoter of the TF FOXA2, which was involved in metabolism, homeostasis, embryo development, and cancer." (PMID 37031183, 2023). "The molecular mechanistic studies revealed that CD44 plays a pivotal role in controlling FOXA2 localization to promote cancer metastasis via the AKT signaling pathway." (PMID 36289750, 2022). "Nonetheless, targeting FOXA2 by various microRNAs has been shown to promote cancer metastasis and proliferation." (PMID 36289750, 2022). "We summarize that CD44 promotes cancer cell migration through the cytosolic localization of FOXA2 mediated by the AKT signaling pathway." (PMID 36289750, 2022). "One of the recent studies showed that FOXA2 (Forkhead Box A2) protein is overexpressed in cancer stem cells and its activity is directly related to the intensity of autophagy." (PMID 33804163, 2021). "MiR-141-3p remarkably raises proliferation, colony formation, invasion and EMT of cancer cells in the cervix to promote tumorigenesis by targeting FOXA2." (PMID 33842488, 2021). "We further showed that FOXA2 is a direct target of miR-590-3p, while Versican (VCAN), a proteoglycan commonly overexpressed in cancer, is transcriptionally inhibited by FOXA2." (PMID 32993038, 2020). "We also found copy number loss of cancer genes such as CCNE1, MAF, MAFB, MYC, ZNF479, and MGMT and copy number gain of FOXA2, CDH10, and GPC5 in at least two WDPM cases." (PMID 32545767, 2020).
cancer (continued). "Another case in which SUMOylation contributes to the stability of a protein related to lipid metabolism during cancer development is the SUMOylation of the transcription factor FOXA2 in the rat insulinoma-cultured cell line, INS-1E." (PMID 32781719, 2020). "Recently, increasing number of literatures have proved FOXA2 plays a critical role in cancer progression." (PMID 32176463, 2020). "The four remaining transcription factors retrieved as potential MRs—DACH1, EPAS1, FOXA2, and FOXM1—have been extensively reported in associations with cancers in literature." (PMID 31503425, 2019). "Western Blot analysis showed that p-ERK1/2 and RAS were highly expressed in cancer cells in which FOXA2 was inhibited by siRNA." (PMID 31689237, 2019). "Here, our data also suggest the implication of the tapRNA FOXA2-DS-S in this process, as well as other tapRNAs affecting metastatic characteristics of different cancer cells." (PMID 29540241, 2018). "FOXA1 and FOXA2 are essential transcription factors in cancer as they are able to bind to their response elements in tightly wrapped nucleosomes." (PMID 28681081, 2018). "FOXA2 expression in cancer cells has been reported to be regulated by several mechanisms, including epigenetic phenomena." (PMID 29137263, 2017). "Several growth factors such as Nodal, Lefty, FGF, HB-EGF and HGF as well as transcription factors (e.g. Pitx2, FoxA2) are considered candidates with overlapping functions in cancer and development laterality." (PMID 27383829, 2016). "The identification of FOXA1 or FOXA2 as essential transcription factors in cancer cells proposes the existence of a conserved role of the FOXA family in the core transcriptional regulatory circuitry." (PMID 27739523, 2016). "It is already known that Foxa2 downregulation is required to elicit epithelial-to-mesenchymal transition (EMT) in various cell lines established from malignant tumors originating in endoderm-derived organs." (PMID 26395490, 2015). "For instance, FOXA1 clearly appears to be responsible for hypomethylation of FOX-containing enhancers in breast (BRCA) and bladder (BLCA) cancers, while FOXA2 appears to be responsible in endometrial (UCEC)." (PMID 25994056, 2015). "The function of Foxa1 has been studied primarily in a variety of cancer cell lines and, together with Foxa2, during embryonic development." (PMID 22737085, 2012). "Specifically, the carcinoma cell lines Caco-2 and HepG2 enabled mechanistic investigations into FOXA2 on HNF6 nuclear protein activity." (PMID 20967225, 2010). "The study also highlights that FOXA1 and FOXA2 have the same or opposite roles in several mammalian stages, which provides a theoretical basis for the future treatment of metabolic diseases, neurodegenerative diseases, and cancers by targeting FOXA1 and FOXA2." (PMID 38605023, 2024). "Furthermore, the article describes the prospect of targeting upstream regulators of FOXA1/FOXA2 to regulate its expression for cancer therapy because of the drug untargetability of FOXA1/FOXA2." (PMID 38605023, 2024). "When FOXA2 was silenced, it drove cancer cell proliferation." (PMID 39129202, 2024). "Although many cell and animal experiments have demonstrated that FOXA1/FOXA2 knockout can significantly inhibit cancer progression, FOXAs themselves are undruggable targets for clinical application because of their intricate transcriptional network as transcription factors." (PMID 38605023, 2024). "Additionally, FOXA2 is downregulated by miR-590-3p in ovarian cancer, which promotes cancer growth and metastasis." (PMID 36289750, 2022).